ESD (esterase D)
Description:
Serine hydrolase involved in the detoxification of formaldehyde.
Synonyms: FGH
Tractability: Small molecule: it has a high-quality binding pocket. PROTAC: ubiquitination databases record sites on it; its protein half-life has been measured; a small molecule that binds it is known.
Target class: Enzyme; Hydrolase
Gene: Protein-coding gene on chromosome 13 (46,770,748 to 46,799,772, reverse strand). Ensembl gene ENSG00000139684.
Subcellular location: Cytoplasm; Cytoplasmic vesicle
Subcellular location (Human Protein Atlas): Golgi apparatus; Cytosol; Nucleoplasm
Pathways (Reactome):
Metabolism: Glutathione conjugation
Gene Ontology:
Molecular function: hydrolase activity, acting on ester bonds; identical protein binding; protein binding; carboxylic ester hydrolase activity; methylumbelliferyl-acetate deacetylase activity; S-formylglutathione hydrolase activity
Biological process: formaldehyde catabolic process
Cellular component: cytosol; extracellular exosome; endoplasmic reticulum lumen; cytoplasm; cytoplasmic vesicle
Genetic constraint (gnomAD): Loss-of-function variants: 19 observed, 18.37 expected, observed/expected ratio (o/e) 1.03, 90% interval 0.72 to 1.51. The upper end of that interval is the gene's LOEUF score, 1.51, which puts it in group 6 of 6, group 1 being the genes least tolerant of losing a copy. Missense variants: 224 observed, 221.45 expected, observed/expected ratio (o/e) 1.01, 90% interval 0.91 to 1.13. Synonymous variants: 73 observed, 74.14 expected, observed/expected ratio (o/e) 0.98, 90% interval 0.81 to 1.2.
Homologues: Orthologues: chimpanzee ESD (99% identical), dog ESD (96% identical), pig ESD (96% identical), guinea pig ESD (92% identical), mouse Esd (92% identical), rat Esd (91% identical), macaque ESD (90% identical), tropical clawed frog esd (80% identical), zebrafish esd (80% identical), Drosophila melanogaster CG4390 (59% identical), Caenorhabditis elegans Y48G10A.1 (52% identical).
Diseases named in the same sentence as ESD in open-access papers:
ESD is named in the same sentence as 15 diseases in open-access papers, as found by Europe PMC text mining. Sharing a sentence is not in itself a finding about the gene and the disease. The quoted sentences say what the papers report.
retinoblastoma (4 papers, 1987 to 2019). A malignant tumor that originates in the nuclear layer of the retina. "While the normal cells in the children expressed both esterase D alleles, the retinoblastoma tumors of 4/6 children expressed only one allele." (PMID 31683923, 2019). "Seven families were informative for the enzyme polymorphism and in all cases cosegregation of the retinoblastoma gene and esterase-D alleles was demonstrated, giving a lod score of 2.61." (PMID 3620311, 1987). "They concluded that retinoblastoma tumorigenesis requires somatic inactivation of the retinoblastoma RB1 locus near the esterase D locus." (PMID 31683923, 2019). "Murphree and others demonstrated low expression of esterase D in patients with partial 13q deletions and retinoblastoma, concluding that the physical location of the gene that imparted retinoblastoma susceptibility was near the esterase D gene on band 13q14." (PMID 31683923, 2019). "The esterase D gene was subsequently cloned and shown to be normal in most retinoblastoma tumors, demonstrating that it was separate from the RB1 locus." (PMID 31683923, 2019). "Since the human enzyme esterase D was known to be overexpressed in children with trisomy 13, esterase D expression was evaluated in retinoblastoma patients with partial deletions or duplications of chromosome 13." (PMID 31683923, 2019). "Genetic polymorphism of esterase D (ESD) and its reduced enzymatic activity was found to be associated with the susceptibility to several pathological conditions like toxic liver cirrhosis, retinoblastoma, Wilson’s disease, obesity and autism." (PMID 24085543, 2013).
lung adenocarcinoma (2 papers, 2013 to 2024). A carcinoma that arises from the lung and is characterized by the presence of malignant glandular epithelial cells. "ABHD11 and Esterase D could predict the development of distant metastases and the presence of aggressive lung adenocarcinomas." (PMID 39190284, 2024).
lung carcinoma (2 papers, 2022 to 2024). "Activation of esterase D (ESD) promotes its interaction with MT2 A, reduces the protein level of MT2 A, up-regulates the concentration of free zinc ions, and inhibits the migration of A549 lung cancer cells in vitro." (PMID 39717098, 2024).
acute myeloid leukemia (1 paper, 2013). Acute myeloid leukemia (AML) is a group of neoplasms arising from precursor cells committed to the myeloid cell-line differentiation. "In conclusion, there are no doubts that esterase D and gamma 1 actin, suggested by the authors to represent prognostic factors involving results of induction therapy in acute myeloid leukemia M1 and M2, should provide targets of further more detailed investigations." (PMID 24085543, 2013).
schizophrenia (1 paper, 2012). A major psychotic disorder characterized by abnormalities in the perception or expression of reality. "Multiple genes encoded by chromosome 13 have been suggested to contribute to schizophrenia susceptibility, including DAOA, 5-HTR2A, KPNA3 and KPNB3, ESD, ATXN8OS, KFL5, EFNB2, and PCDH8." (PMID 22214315, 2012).
cancer (2 papers, 2019 to 2023). A tumor composed of atypical neoplastic, often pleomorphic cells that invade other tissues. "The third Speg-dependent component of the ECC complex is Esterase D, a widely expressed esterase with both carboxylesterase and thioesterase activity that plays critical roles in drug metabolism and suppression of cancer growth." (PMID 37709832, 2023).
tumor (2 papers, 2019). "Compared to the expression levels in normal tissue, other genes, such as ADRB3, BTG2, DUSP4, RAD51 or FBLX7, were downregulated in specific tumor types, and ANG, ESD and STL7 were downregulated in most tumor types." (PMID 31159852, 2019).
ESD also shares sentences with these, for which no sentence is quoted: anemia (1 paper); autism (1); infection (1); neuroblastoma (1); non-small cell lung carcinoma (1); Obesity (1); uveitis (1); Wilson disease (1).